BMP7 (bone morphogenetic protein 7)
Diseases named in the same sentence as BMP7 in open-access papers (continued):
Sharing a sentence is not in itself a finding about the gene and the disease.
Hypercholesterolemia (1 paper, 2023). An increased concentration of cholesterol in the blood. "A significant decrease in these cell signaling markers were observed following BMP-7 treatment, suggesting the efficacy of BMP-7 in attenuating hypercholesterolemia-induced TGF-β1, Smad2, and Smad3 proteins." (PMID 36829889, 2023).
Hypertension (1 paper, 2022). The presence of chronic increased pressure in the systemic arterial system. "The development of renal damage, hypertension, and increased pulse wave velocity (PWV) in CKD might be associated with an imbalance in bone morphogenetic proteins (BMP)-2 and BMP-7." (PMID 36613483, 2022).
IgA nephropathy (1 paper, 2023). "For example, in IgA nephropathy, glomerular fibrosis results from IgA activation of mesangial cells to secrete TNF-α, IL-6 and TGF-β and in patients with IgA nephropathy, significantly reduced levels of glomerular BMP-7 were demonstrated in renal biopsy samples." (PMID 37626268, 2023).
leiomyoma (1 paper, 2023). A well-circumscribed benign smooth muscle neoplasm characterized by the presence of spindle cells with cigar-shaped nuclei, interlacing fascicles, and a whorled pattern. "The involvement of many proteins such as FN1, COL1A1, BMP7, CCND1, EZH2, HMGA2, AhR, and E2F1 shown in the protein–protein interaction networks are well known in leiomyoma pathogenesis; others, such as SOX2, REN, PPARG, ABCB1, and NR3C1 are novel and require further investigation." (PMID 36835153, 2023).
liver cirrhosis (1 paper, 2022). "Ribera and his colleagues showed the mesenchymal phenotype of ECs in CCl4-induced liver cirrhosis via bone morphogenic protein-7 (BMP-7)/TGF-β signaling." (PMID 35053347, 2022).
metastatic melanoma (1 paper, 2012). A melanoma that has spread from its primary site to another anatomic site. "Similarly, aggressive metastatic melanoma cells have been shown to be resistant to autocrine growth-inhibitory effects of BMP-7." (PMID 23049692, 2012).
mucinous carcinomas (1 paper, 2023). "High calpain‐1 expression was linked with the presence of residual disease and HGSC (as seen in high BMP7 expression) and low calpain‐1 expression was linked with low stage, no residual disease and clear cell, endometrioid and mucinous carcinomas." (PMID 37688374, 2023).
muscle atrophy (1 paper, 2022). The loss of muscle tissue due to inactivity or disease. "A recent approach is the administration of BMP-7 (bone morphogenetic protein 7), which, in mice, showed the potential to attenuate pyroptosis, inflammation, and muscle atrophy in diabetic muscle myopathy via the inhibition of the HMGB-1 protein." (PMID 35954203, 2022).
myopia (1 paper, 2011). "In humans, mutations in BMP-4 and BMP-7 have been reported to be associated with eye and brain developmental anomalies, including the development of myopia in specific families." (PMID 21403850, 2011).
nephrosclerosis (1 paper, 2010). Hardening of the kidney due to infiltration by fibrous connective tissue (fibrosis), usually caused by renovascular diseases or chronic hypertension. "BMP-7 mRNA was significantly reduced in the tubulointerstitium of patients with nephrosclerosis (relative median quantity with quartiles: 0.25 (0.14 - 0.42)) compared to normal kidneys (0.69 (0.28 - 0.83), p < 0.01)." (PMID 21080950, 2010). "Levels of glomerular BMP-7 mRNA did not significantly differ among patients with nephrosclerosis (0.26 (0.14 - 0.54)) compared to those without kidney diseases (0.19 (0.13 - 0.30), p = 0.561)." (PMID 21080950, 2010).
non-small cell lung carcinoma (1 paper, 2022). A group of at least three distinct histological types of lung cancer, including non-small cell squamous cell carcinoma, adenocarcinoma, and large cell carcinoma. "In hepatocellular carcinoma, expression of BMP4 and BMP7 was increased, but advanced non-small cell lung cancer was associated with increased BMP2 serum levels and correlated with poor outcomes." (PMID 36353620, 2022). "Conversely, when BMP7 was neutralized or knocked down, anti-PD1 non-small cell lung cancer tumors were re-sensitized to immunotherapy." (PMID 36353620, 2022).
orofacial cleft (1 paper, 2015). A disorder of facial skeleton that is characterized by cleft lip and/or cleft palate that result in feeding, speech and hearing problems caused by failures during development. "Key words:Single nucleotide polymorphisms, nonsyndromic orofacial clefts, BMP7." (PMID 25662552, 2015).
ovarian adenocarcinoma (1 paper, 2019). An adenocarcinoma that arises from the ovary. "As PEO1 was derived from ascitic fluid of a patient with ovarian adenocarcinoma whilst PEO4 was derived from the ascites of the same patient at the time of relapse the COL3A, and BMP7 differential expression, in the current study, may be of interest in terms of tumour progression." (PMID 30448882, 2019).
pancreatic neuroendocrine tumor (1 paper, 2015). Pancreatic endocrine tumor, also known as pancreatic neuroendocrine tumor (PNET), describes a group of endocrine tumors originating in the pancreas that are usually indolent and benign, but may have the potential to be malignant. "The expression of GREM1, a bone morphogenetic protein antagonist, correlates with increased angiogenesis in humans with pancreatic neuroendocrine tumors; whereas, the knock-down of GREM1 in human HK–2 cells increases BMP7 signaling activity." (PMID 26445145, 2015).
pituitary adenomas (1 paper, 2013). "The role of BMP2, BMP4 and BMP7 as signalling peptides in the programming of pituitary development makes them plausible candidates for pituitary disorders including congenital insufficiency as well as pituitary adenomas." (PMID 24289245, 2013).
polycystic ovary syndrome (1 paper, 2022). A disorder that manifests as multiple cysts on the ovaries. "Previous studies have shown that several BMPs, including BMP2, BMP4, BMP5, BMP6, BMP7 and BMP8A are expressed in the granulosa cells from normally cycling and polycystic ovary syndrome women." (PMID 35395768, 2022).
polyp (1 paper, 2024). A usually exophytic mass attached to the underlying tissue by a broad base or a thin stalk. "Significant dysregulation of the expression of critical genes, including DKK1, GPC3, BMP7, FGF17, and WNT10B, was observed in the PPI network; this dysregulation could potentially be associated with the proliferation of polyp tissues." (PMID 38473810, 2024).
proliferative vitreoretinopathy (1 paper, 2022). Vitreoretinal membrane shrinkage or contraction secondary to the proliferation of primarily retinal pigment epithelial cells and glial cells, particularly fibrous astrocytes, followed by membrane formation. "A previous study showed that BMP7 could reduce proliferative vitreoretinopathy, a major complication of end-stage retinal detachment, by inhibiting RPE cells’ fibrosis in a rabbit model." (PMID 36408112, 2022).
Pseudoarthrosis (1 paper, 2013). A pathologic entity characterized by a developmental defect in a long bone leading to bending and pathologic fracture, with inability to form a normal bony callus with subsequent fibrous nonunion, leading to the pseudarthrosis (or "false joint"). "It is a randomized prospective trial that compared recombinant bone morphogenetic protein 7–rhBMP-7 with PRP for the treatment of pseudoarthrosis." (PMID 23579757, 2013).
pulmonary arterial hypertension (1 paper, 2025). Pulmonary arterial hypertension (PAH) is a group of diseases characterized by mean pulmonary artery pressure >20 mmHg and elevated pulmonary arterial resistance leading to right heart failure. "Via in vitro and in vivo studies based on hypoxia-induced pulmonary arterial hypertension (PAH) and pulmonary artery ECs, the role of BMP-7 as inhibitor of hypoxia-induced EndMT and cell migration was demonstrated." (PMID 40650130, 2025).
radiation pneumonitis (1 paper, 2024). Inflammation of the lung due to harmful effects of ionizing or non-ionizing radiation. "In this study, the inhibition of TGF-beta (one of the most potent fibrotic indicator) by OT and the secondary increase in the level of BMP-7, which decreases the effect of TGF-beta, proved that OT suppresses the early fibrotic process in radiation pneumonitis." (PMID 39330747, 2024).
renal agenesis (1 paper, 2011). Renal agenesis (RA) is a form of renal tract malformation characterized by the complete absence of development of one or both kidneys (unilateral RA or bilateral RA respectively), accompanied by absent ureter(s). "Prevalence of the complete renal agenesis in Bmp7 and Grem1-deficient and compound mutant mice at birth." (PMID 21552539, 2011). "As expected, bilateral renal agenesis was observed in about 90% of all Grem1-deficient mice at birth in the presence of either one or two functional Bmp7 alleles." (PMID 21552539, 2011). "Genetic inactivation of one Bmp7 allele in Grem1-deficient mouse embryos does not alleviate the bilateral renal agenesis, while complete inactivation of Bmp7 restores ureteric bud outgrowth and branching." (PMID 21552539, 2011).
renal dysfunction (1 paper, 2022). "The imbalance between BMP-2 and BMP-7 in the kidney is reflected as albuminuria, supporting the link between vascular and renal dysfunction." (PMID 36613483, 2022).
renal osteodystrophy (1 paper, 2018). Abnormalities of bone mineral metabolism associated with chronic kidney disease. "Furthermore it was examined whether the P-lowering effect of BMP7 might be due to amelioration of renal osteodystrophy and hereby increased P uptake into bone." (PMID 29304096, 2018).
rheumatic disease (1 paper, 2023). "Pre-clinical data showing a therapeutic effect of BMP-7 in rheumatic disease specifically, is available." (PMID 37626268, 2023).
sarcoma (1 paper, 2016). A usually aggressive malignant neoplasm of the soft tissue or bone. "To discount prognostic influences of BMPR1A, BMPR1B or BMP2 expression individually, we constructed Kaplan-Myer curves for the entire sarcoma dataset and compared patients with the highest and lowest 10% expression of BMPR1A, BMPR1B, BMPR2, BMP2 and BMP7." (PMID 27114889, 2016).
schistosomiasis (1 paper, 2017). An infectious disease caused by parasitic trematodes of the genus Schistosoma that colonize human blood vessels and release eggs that can cause granulomatous reactions leading to acute (swimmer's itch or acute schistosomiasis syndrome) or chronic disease. "In a model of hepato-schistosomiasis-induced fibrosis, recombinant BMP7 reduced histopathological features of fibrotic lesion and diminished TGF-β1 and αSMA expression in liver, results that again suggest that BMP7-antifibrotic effects might be dependent on its action on the TGF-β pathway." (PMID 29295498, 2017).
secondary hyperparathyroidism (1 paper, 2018). Overproduction of parathyroid hormone in response to influence external to the parathyroid glands. "In animal models of CKD-MBD with established secondary hyperparathyroidism, BMP7 administration stimulates bone formation and increases bone mass, and in animal models with adynamic bone disease BMP7 restores skeletal remodelling to normal rate." (PMID 29304096, 2018).
serous carcinomas (1 paper, 2023). "A significant association was found between high cytoplasmic and nuclear BMP7 expression and high‐grade serous carcinomas (HGSC)." (PMID 37688374, 2023). "Elevated cytoplasmic and nuclear BMP7 expression was significantly associated with advanced FIGO stage, high tumour grade, presence of residual tumours and high‐grade serous carcinomas (p = 0.001, 0.005, 0.004, <0.001 and p < 0.001, <0.001, 0.002, 0.001 respectively)." (PMID 37688374, 2023).
squamous cell carcinoma (1 paper, 2022). A carcinoma arising from squamous epithelial cells. "In addition, depletion of TGFβ2 in FSP1+ CAFs has been shown to induce squamous cell carcinoma in the murine forestomach, associated with the upregulation of bone morphogenetic protein 7 (BMP7), SMAD1/5/8 and HGF." (PMID 36671452, 2022).
Truncus arteriosus (1 paper, 2019). A single arterial trunk arises from the cardiac mass. "While Bmp7 null mutants do not show defects in heart development, conditional deletion of both Bmp7 and Bmp4 from progenitors of the secondary heart field leads to persistent truncus arteriosus." (PMID 31566563, 2019).
uremia (1 paper, 2018). A clinical syndrome associated with the retention of renal waste products or uremic toxins in the blood. "BMP7 treatment caused a significant decrease of plasma phosphate to 1.56 ± 0.17 mmol/L vs 2.06 ± 0.34 mmol/L in the vehicle group even in the setting of uremia and high phosphate diet." (PMID 29304096, 2018). "The BMP7 treatment resulted in a significant decrease in plasma P despite persistent uremia and a high P diet." (PMID 29304096, 2018). "The decrease in t-cadherin expression by BMP7 treatment might potentially improve vascular function in uremia." (PMID 29304096, 2018). "Uremia and alfacalcidol resulted in an increase in aortic expression of genes related to fibrosis, osteogenic transformation and extracellular matrix calcification, and the BMP7 treatment resulted in a decrease in the expression of profibrotic genes." (PMID 29304096, 2018). "It is highly interesting as high plasma P by itself is a vascular toxin in uremia and as the reduction during BMP7 treatment in the present study occurs despite no improvement in kidney function." (PMID 29304096, 2018). "Treatment with BMP7 resulted in normalization of plasma phosphate which potentially may have beneficial effects on the vasculature in uremia independent of BMP7." (PMID 29304096, 2018).
urothelial carcinoma (1 paper, 2023). A malignant neoplasm derived from the transitional epithelium of the urinary tract (urinary bladder, ureter, urethra, or renal pelvis). "In addition, BMP7 expression in infiltrating urothelial carcinoma was associated with better progression‐free survival as high BMP7 expression was associated with a prolonged time to recurrence." (PMID 37688374, 2023).
tumor (147 papers, 2008 to 2025). "Mechanistically, the progression of CRC is exacerbated by mutations in TGF-beta pathway genes, like BMP7; this mutation allows tumor cells to escape growth-inhibitory effects and evade apoptosis." (PMID 39682092, 2024). "By grouping cases into two categories—organ‐confined or spread data suggest that high cytoplasmic and nuclear BMP7 expression were significantly associated with tumours that had spread past the primary organ." (PMID 37688374, 2023). "High BMP7 cytoplasmic expression associated with high tumour grade (χ2 = 10.700, d.f. = 2, p = 0.005) and high FIGO stage (χ2 = 16.762, d.f. = 3, p = 0.001)." (PMID 37688374, 2023). "High cytoplasmic and nuclear BMP7 expression was significantly associated with residual tumours of greater size (>2 cm)." (PMID 37688374, 2023). "High BMP7 cytoplasmic and nuclear expression were also significantly associated with high tumour grade." (PMID 37688374, 2023). "High BMP7 nuclear expression also linked to the same variables as with high cytoplasmic expression, including high tumour grade (χ2 = 15.876, d.f. = 2, p < 0.001) and high FIGO stage (χ2 = 18.039, d.f. = 3, p < 0.001)." (PMID 37688374, 2023). "Our group looked at the effects of BMP7 in an anti-PD1 tumor model involving a variant of a murine lung cancer cell line." (PMID 36353620, 2022). "Epithelial-associated genes KRT20 and BMP7 were consistenantly upregulated in all blood samples as compared to tumours." (PMID 35493092, 2022). "Conversely, other studies have shown BMP-7 overexpression in primary tumours associated with bone metastases." (PMID 28733469, 2017). "BMP7 expression in primary tumour seems to correlate with the risk for accelerated BM formation in BC patients." (PMID 28194227, 2017). "In this study, we demonstrate that the BMP7 protein is highly expressed in 72% of human tumors and it associates with tumor location (more frequently elevated in PGLs than in PCCs) and tumor size (higher in large PCCs)." (PMID 26337467, 2015). "By contrast, Bmp7‐GOF caused a ≈100% increase of 4T1 tumor growth in nude mice." (PMID 38708713, 2024). "In addition to BMP4, also elevated levels of other members of the BMP-family, including BMP6 and BMP7, have been linked to increased tumor aggressiveness." (PMID 31694641, 2019). "BMP7 is one of the most frequently mutated tumor suppressors in human cancer including HCCs." (PMID 26503415, 2015). "Thus, in human PCCs, BMP7 is highly expressed and its levels positively associate with tumor size and origin (extra-adrenal)." (PMID 26337467, 2015). "Lactate upregulates the lactylation level of histone H4K8 and activates the transcription of target gene BMP7, ultimately facilitating tumor progression." (PMID 40470706, 2025). "Studies of BMP7 are less conclusive, as high BMP7 correlates with advanced tumour stage and poor prognosis." (PMID 40212011, 2025). "Reduced BMP7 expression has been correlated with tumor progression and drug resistance across multiple cancers." (PMID 41395597, 2025). "IHC staining for Ki‐67 and TUNEL further confirmed the increased proliferative capacity and reduced apoptosis in tumor tissues from BMP7‐overexpressing mice." (PMID 40470706, 2025). "It is critically involved in tumor cell proliferation, growth, and metastasis by regulating various proteins, such as bone morphogenetic protein 7 (BMP7)." (PMID 40255403, 2025). "BMP2, BMP4, and BMP7 are canonical growth-inhibitory ligands known to suppress tumor progression by inducing apoptosis and inhibiting EMT in CRC and other cancers." (PMID 40564222, 2025). "In PANC-1 cells, treatment with TGF-β1 or, surprisingly, BMP-7 downregulated ECAD and another epithelial marker, RAC1b (a tumor-associated splice isoform of human RAC1)." (PMID 39682758, 2024). "In tumor progression, BMP-7 inhibits tumor epithelial-to-mesenchymal transition (EMT) and TGF-β-mediated cell migration and invasion." (PMID 38892327, 2024).